GDF15 (growth differentiation factor 15)
Diseases named in the same sentence as GDF15 in open-access papers (continued):
Sharing a sentence is not in itself a finding about the gene and the disease.
coronary artery disease (110 papers, 2012 to 2026). "Elevated circulating levels of GDF15 have been linked to a heightened risk of coronary artery disease, pathological cardiac remodeling, and the onset of heart failure." (PMID 40806859, 2025). "Specifically, GDF15 was identified as the highest-ranking protein associated with coronary artery disease in a proteomic study, and was described as a mortality predictor in both patients with acute coronary syndrome and stable coronary artery disease." (PMID 41008541, 2025). "Next to GDF-15, the soluble form of uPAR has been identified as an independent predictor of all-cause death in patients with coronary artery disease." (PMID 38398274, 2024). "Serum GDF-15 levels were elevated in acute coronary syndrome, severe coronary artery disease, and the major Japanese version of the high bleeding risk criteria." (PMID 37396418, 2023). "GDF-15 is also associated with major adverse cardiovascular events in patients with coronary artery disease." (PMID 37484982, 2023). "Increased circulating GDF-15 is significantly associated with significant cardiovascular events in patients with coronary artery disease, major bleeding in patients receiving antithrombotic therapies, chronic kidney diseases, and cancers." (PMID 37152099, 2023). "High levels of GDF-15 are associated with increased mortality linked to cardiovascular diseases, such as heart problems, coronary artery disease, atrial fibrillation, T2D and cognitive impairment." (PMID 35159548, 2022). "GDF-15 has been associated with bleeding complications in numerous studies, including patients with coronary artery disease on dual antiplatelet therapy (DAPT) and patients with atrial fibrillation on oral anticoagulation." (PMID 35455481, 2022). "The clinical study suggested that a high level of GDF-15 is associated with coronary artery disease, a disease involving chronic inflammatory atherosclerosis." (PMID 34539804, 2021). "In fourteen thousand five hundred and seventy-seven patients with stable coronary heart disease, the highest quartile of GDF-15 concentrations was highly associated with all-cause morbidity and with stroke." (PMID 31258506, 2019). "Indeed, in patients with stable coronary artery disease a number of coincidental risk factors for cardiovascular disease have been shown to significantly affect plasma GDF15 concentration." (PMID 32310257, 2020). "We add new evidence that GDF-15 > 1800 ng/L maybe a high risk critical range for patients with coronary heart disease." (PMID 32746821, 2020). "Interestingly, GDF-15 is associated with reduced risk of coronary heart disease and breast cancer (OR: 0.93 and OR: 0.89, respectively) but not with T2DM and CRC risk factors." (PMID 31831021, 2019). "This classification is supported by consistent findings that GDF-15 is associated with both disease-specific outcomes and all-cause mortality in the setting of various conditions, including cancer, stable coronary heart disease, atrial fibrillation, and acute coronary syndrome." (PMID 29714603, 2018). "In addition we evaluated the possible association of GDF-15 with the complexity of the coronary disease." (PMID 28771550, 2017). "And this hypothesis is supported by a recent study on the association of GDF-15 and coronary diseases." (PMID 26075263, 2015). "GDF-15 has emerged as a strong and independent predictor of all-cause and cardiovascular mortality in patients with heart failure and different manifestations of ischemic heart disease." (PMID 24312445, 2013). "This study uniquely included a healthy control group and provided a comprehensive analysis of GDF-15 regarding macrovascular diseases, such as DN, coronary heart disease, and cerebral infarction." (PMID 41019919, 2025). "Although elevated circulating GDF15 level is typically associated with poor prognosis in patients with coronary heart diseases including MI176,177, GDF15-enriched rEVs appear to be cardioprotective, warranting further investigation." (PMID 41034526, 2025).
coronary artery disease (continued). "In coronary heart disease patients, the levels of growth differentiation factor 15 (GDF-15) in PF are correlated with LVEF, biomarkers of renal dysfunction, and inflammatory molecules." (PMID 39125899, 2024). "Determination of the combination of GDF-15, IL-6, LCN-2, and TIM-3 markers can indeed complement coronary angiography in the diagnosis, risk assessment, and management of coronary artery disease (CAD)." (PMID 39330316, 2024). "The prognostic value of GDF-15 in coronary disease, on the other hand, has been reported in numerous studies, where high levels consistently predict mortality from 30 days up to 10 years after MI, and correlates to ischemic injury." (PMID 38739599, 2024). "Studies investigating GDF-15 in coronary artery disease (CAD) have shown its potential as a predictive biomarker for acute coronary syndrome (ACS) recurrence, MI-related complications, HF, and mortality." (PMID 38791250, 2024). "In particular, with regard to the heart, GDF-15 predicts morbidity and mortality in stable coronary heart disease." (PMID 38398274, 2024). "(2020) in men with coronary artery disease, GDF-15 levels correlated inversely with serum testosterone levels and testosterone-to-estradiol ratio." (PMID 39420932, 2024). "Serum GDF-15 levels were elevated in patients with severe coronary artery disease, such as left main trunk lesions and 3-vessel disease." (PMID 37396418, 2023). "This study also put forward the potential benefit of using GDF-15 as a predictor of death due to major bleeding in coronary heart disease." (PMID 36676179, 2023). "Serum circulating levels of GDF-15 can reflect the inflammatory process in atherosclerosis and coronary artery disease." (PMID 37484982, 2023). "GDF-15 has been recognized as a reliable biomarker of acute cardiovascular events in patients with acute coronary syndrome or stable coronary artery disease." (PMID 37371667, 2023). "In coronary artery disease patients, GDF-15 serum level was found to be significantly elevated compared to healthy controls." (PMID 34221186, 2021). "In previous studies, increased GDF-15 levels were associated with MI, stroke and cardiovascular death, as well as with reduced LVEF, coronary artery disease and HF in the elderly." (PMID 32466218, 2020). "The aim of the present cohort study is to investigate the prognostic value of GDF-15 in patients with coronary artery disease (CAD) during long-term follow up." (PMID 32746821, 2020). "Most studies on GDF-15 in cardiovascular disease have focused on coronary artery diseases, since this biomarker is strongly related to infarcted human heart." (PMID 32466218, 2020). "In men with coronary artery disease, GDF15 levels were inversely correlated to serum testosterone and testosterone/estradiol ratio, but not to estradiol." (PMID 32857481, 2020). "Clinical studies have also shown that the GDF-15 concentration correlated strongly with age in healthy elderly individuals and patients with coronary artery diseases." (PMID 31581569, 2019). "During the progress of coronary heart disease, serum GDF-15 levels were closely related to the aggravation of the disease, which suggested a higher incidence of acute cardiac events." (PMID 31772623, 2019). "The aim of the present study was to investigate the prognostic value of a single measurement of GDF-15 for prediction of the development of HF and death due to coronary heart disease (CHD) in the general population." (PMID 29771963, 2018). "GDF-15 can be used as a novel biomarker for the detection of PMI of the OPCAB surgery in patients with coronary artery disease." (PMID 27311391, 2016). "We aimed to investigate determinants of GDF-15 plasma levels in patients with angiographically proven coronary artery disease (CAD)." (PMID 27056183, 2016).
coronary artery disease (continued). "In the cardiovascular system, GDF-15 is now identified as a strong prognosis marker in patients with cardiovascular disease, including coronary artery disease (CAD), acute coronary syndromes (ACS) and heart failure (HF)." (PMID 25171167, 2014). "In patients with coronary artery disease, atrial fibrillation, and HF, GDF-15 may provide additional prognostic information, offering valuable insights into patient outcomes." (PMID 39273041, 2024). "Moreover, previous studies have demonstrated a correlation of GDF-15 with bleeding complications in patients with coronary artery disease on dual antiplatelet therapy (DAPT)." (PMID 36836162, 2023). "Regarding CVD, levels of GDF-15 have been associated with cardiovascular events in the general population with a history of acute coronary syndrome or stable coronary artery diseases (CAD) and also in absence of any CVD history." (PMID 36093162, 2022). "Thus, GDF15 circulating levels strongly associate with mortality across a spectrum of CVD states, including chest pain, acute coronary syndromes, stable coronary heart disease (CHD), and heart failure." (PMID 35160008, 2022). "A recent study proposed a GDF15 cut-off value for the diagnosis of coronary artery disease." (PMID 36430499, 2022). "Moreover, GDF-15 significantly contributes to subclinical coronary heart disease (CHD) independently of established cardiovascular disease (CVD) risks and has been frequently associated with CVD." (PMID 34920697, 2021). "In addition, those males who had CAC score > 400, reflecting severe coronary artery disease, had higher GDF-15 concentration." (PMID 34526107, 2021). "Accordingly, given its involvement in the response to cardiac stress and myocardial ischemia as well as coronary artery disease, the observed decrease in GDF-15 further supports the assumption of a reduction in cardiac stress and ischemia in response to microgravity." (PMID 32423045, 2020). "However, the correlation between GDF15 and diabetic cardiovascular complications has mostly been investigated with regard to myocardial or coronary artery diseases, and few data have been reported about GDF15 and LEAD." (PMID 32222153, 2020). "Several groups have shown recently that growth differentiation factor 15 (GDF15), also known as MIC-1, is an independent predictor of all-cause mortality in white elderly (>70 years) individuals, whites with coronary heart disease and also in white middle-aged individuals." (PMID 32764826, 2020). "Recent studies have investigated the relationship between GDF-15 levels and metformin effects, particularly in the context of T2DM, obesity, postprandial states, coronary artery disease, and cancer." (PMID 39420932, 2024). "In a different study (Mendelian randomization), the impacts of growth differentiation factor 15 (GDF-15), a potential biomarker for metformin intake was investigated on coronary heart disease, breast cancer, and CRC was evaluated." (PMID 31831021, 2019). "GDF-15 has been introduced as a prognostic marker for patients with coronary artery disease (CAD) especially in the case of acute non-ST-elevation myocardial infarction (NSTEMI)." (PMID 27056183, 2016). "There were also significant independent relations between GDF-15 and previous cardiovascular or coronary heart disease and stroke morbidity, but not with previous cancer." (PMID 24312445, 2013). "Although metformin does not directly affect coronary artery disease through the GDF‐15 pathway, the GDF‐15 dependent weight loss effect may contribute to higher insulin sensitivity." (PMID 33392433, 2020). "In addition, GDF-15 was reported to be correlated with cardiovascular and noncardiovascular mortality, and it played important roles in multiple cardiovascular diseases, such as heart failure, cardiac hypertrophy, and coronary heart disease." (PMID 34539804, 2021).
coronary artery disease (continued). "Interestingly, in this community-dwelling cohort with 3,428 participants GDF-15 as well as the other biomarkers soluble ST2 (sST2) and high-sensitivity troponin I (hsTnI) did not predict coronary artery disease events, but total mortality." (PMID 29771963, 2018). "The predictive value of GDF-15 in ACS has been confirmed in the 2 large non-ST-segment-elevation ACS (NSTE-ACS) trials: the GUSTO-IV (Global Utilization of Strategies to Open Occluded Arteries IV) and FRISC II (Fast Revascularization during Instability in Coronary Artery Disease II) cohorts." (PMID 32746821, 2020).
Anorexia (102 papers, 2012 to 2026). Lack of desire to eat (loss of appetite). "In line with this, we also report elevated liver expression of GDF15 in the anx/anx mouse displaying anorexia associated with mitochondrial dysfunction." (PMID 40562759, 2025). "Both hepatic IRE1α knockout and IRE1α ribonuclease inhibitors markedly attenuate liver Gdf15 production and reduce circulating GDF15 concentrations, leading to improved chemotherapy-associated anorexia and body mass reduction." (PMID 40837873, 2025). "In conditions such as cancer cachexia and chemotherapy-induced anorexia, increased GDF15 concentrations have been associated with appetite suppression through the activation of emetic and nausea-related pathways." (PMID 41301477, 2025). "Previous publications indicate a causal role of GDF15 in tumour‐induced anorexia, weight loss, muscle function decline and exercise intolerance." (PMID 39976232, 2025). "GDF‐15, a member of the transforming growth factor‐beta superfamily, is known to induce anorexia and weight loss, leading to muscle atrophy in patients with cancer." (PMID 41380167, 2025). "According to these models, anorexia was associated with GDF15 and IL-6 concentrations above at least 131 pg/mL and 450 pg/mL, respectively." (PMID 40124481, 2025). "High serum GDF‐15 levels are associated with poor prognosis in patients with cancer due to their role in inducing anorexia, weight loss and muscle degradation, further worsening sarcopenia and diminishing physical resilience." (PMID 41380167, 2025). "Growth Differentiation Factor 15 (GDF15) is strongly associated with cancer cachexia, as it promotes weight loss through anorexia in animal models." (PMID 40519290, 2025). "In T. gondii infection, GDF15 expression is driven by IFNγ and is critical for the sickness‐induced anorexia and weight loss associated with this disease." (PMID 39428707, 2025). "TCMCB07+GDF15 antibody combination therapy enhances effectiveness in reversing chemotherapy-induced anorexia and weight loss." (PMID 39509261, 2024). "Consistent with previous reports, the effectiveness of the GDF15 antibody was validated in mitigating cisplatin-induced anorexia and weight loss." (PMID 39509261, 2024). "To test for possible synergistic effects of this combination therapy in reversing anorexia and weight loss following higher doses and multiple cycles of chemotherapy, we first measured GDF15 levels in serum samples collected from TCMCB07/chemotherapy studies." (PMID 39509261, 2024). "An increase in circulating GDF15 has been reported to contribute to anorexia and weight loss in a preclinical model of cardiac cachexia." (PMID 38041133, 2023). "Cotreatment of GDF15 antibody mAb2 with MCT prevented MCT-induced anorexia and weight loss, as well as preserved lean and fat mass." (PMID 35406637, 2022). "GDF15 has been repeatedly shown to cause anorexia and food aversion as part of the biological role of the peptide." (PMID 35202387, 2022). "Growth and differentiation factor 15 (GDF15) is a cytokine reported to cause anorexia and weight loss in animal models." (PMID 35406637, 2022). "GDF15 mAb2 completely prevented MCT-induced anorexia and weight loss, including lean and fat mass loss." (PMID 35406637, 2022). "Blocking the GDF15/GFRAL pathway genetically or pharmacologically has demonstrated robust effects in mitigating anorexia and weight loss induced by tumor and/or cisplatin in preclinical models." (PMID 35406637, 2022). "Our results, for the first time, demonstrate that elevated circulating GDF15 is causal to anorexia and weight loss in a cardiac cachexia preclinical model." (PMID 35406637, 2022). "Available evidence suggests that anorexia, as well as “nausea” and emesis induced by cisplatin is associated with increase of growth differentiation factor 15 (GDF15)." (PMID 34925008, 2021).